MTOR (mechanistic target of rapamycin kinase)
Diseases named in the same sentence as MTOR in open-access papers (continued):
Sharing a sentence is not in itself a finding about the gene and the disease.
cyst (continued). "Most of the dual PI3K/mTOR inhibitors tested showed potent inhibition of forskolin-induced cyst growth." (PMID 28644734, 2017). "Rapamycin decreases the proliferation of CD133+ and CD24+ cells and cyst formation in vitro through inhibition of the mechanistic target of rapamycin (mTOR) in PKD." (PMID 28535817, 2017). "When PC1 is inactivated, cyst-lining epithelial cells show activation of mTOR as measured by phosphorylation of mTOR and S6 kinase, a downstream effector." (PMID 28529994, 2016). "The mTOR pathway is inappropriately activated in cyst-lining epithelial cells in human ADPKD patients and mouse models." (PMID 26110849, 2015). "The fact that some cysts in ADPKD tissue and Pkd1 mutant kidneys do not appear to upregulate mTORC1 and the small number of cysts in patients with TSC calls into question the essential role of the mTOR cascade in cyst formation." (PMID 26077033, 2015). "Application of mTOR inhibitor rapamycin reduced the size of cyst-like structures formed by hICD expressing cells, which indicates that the mTOR signaling pathway is a potential therapeutic target for ARPKD." (PMID 24851866, 2014). "It was reported that mTOR is activated in cyst-lining cells in human ADPKD kidneys and inhibition of mTOR pathway reverses renal cystogenesis in animal models, although clinical trials with rapamycin in human ADPKD patients were disappointing." (PMID 24851866, 2014). "Mutations in PC1 disrupt this interaction, unleashing mTOR and in turn, promote the proliferation of cyst-lining epithelial cells in ADPKD by aberrant signaling through mTOR." (PMID 24009738, 2013). "A similar phenomenon has been reported in epithelial cells of the kidney where defects in the primary cilium results in uncontrolled proliferation characterized by high mTOR activity, cyst formation, and ultimately in polycystic kidney disease (PKD)." (PMID 22969057, 2012). "CsA was replaced by sirolimus, an mTOR inhibitor, in order to reduce or control the increase in the cyst and liver volume." (PMID 23304619, 2012). "Induction of phospho-mTOR and p70S6K has been demonstrated in cyst-lining epithelial cells in cysts both from mouse and human kidneys." (PMID 22253885, 2012). "As both proteins inhibit mTOR, a kinase controlling cell proliferation, it is possible to reduce cyst growth by treatment with the mTOR inhibitor rapamycin." (PMID 17357787, 2007). "The mammalian target of rapamycin (mTOR) inhibitors, such as rapamycin, are now being recognized as having salutary effects in cyst formation and disease progression in human and animal models of ADPKD." (PMID 17714589, 2007). "Thus, the general strategy of mTOR inhibition demonstrated efficacy in reducing cyst growth in PKD organoids." (PMID 39855202, 2025). "By day 14 of treatment, the endpoint of this study, the difference in cyst growth was approximately 2-fold for intermediate doses of mTOR inhibitors, compared to the controls, and reached a high level of statistical significance for each of the mTOR inhibitors at every dose." (PMID 39855202, 2025). "Importantly, partial inhibition of mTORC1 in this model normalized ciliary length and reduced cyst development, highlighting the interplay between mTOR signaling and ciliary dynamics in ADPKD pathophysiology." (PMID 40801635, 2025). "Notably, the mTOR inhibitor rapamycin has been shown to reduce cyst growth in preclinical PKD models, underscoring the significance of this pathway." (PMID 40507782, 2025). "As neurofibromin is expressed in tubules and both neurofibromin and PC1 regulate Ras signaling, we speculate that NF1 may enhance ADPKD-driven mTOR signaling, potentially accelerating cyst enlargement." (PMID 40051696, 2025). "Our lab and others have shown that mTOR is a crucial driver of cyst growth in PKD." (PMID 39314240, 2024).
cyst (continued). "Furthermore, whereas control spermatogonial cells divide in synchrony with the other cells of the cyst, single dividing germ cells can be seen several cell- diameters away from the hub upon mTor-depletion." (PMID 38512882, 2024). "In addition, proliferating cyst cells were observed in contact with the hub upon germline depletion of mTor, in proportions similar to control testes." (PMID 38512882, 2024). "Therefore, forcing tissue to use acetone, acetoacetic acid, and beta-hydroxybutyrate (BHB) induces a state of nutrient deficiency leading to mTOR inhibition and activation of AMPK and slowing cyst growth." (PMID 37299584, 2023). "A ketogenic diet, calorie restriction, intermittent fasting, and time-restricted feeding can reduce aerobic glycolysis and inhibit the mTOR pathway, producing a reduction in cyst cell proliferation, a reduction in kidney volume, and helping to preserve kidney function." (PMID 37299584, 2023). "One is that mTOR was aberrantly activated in a certain portion of cyst-lining cells." (PMID 36627370, 2023). "Levels of mTOR, phosphorylated S6K (P-S6K), and phosphorylated S6 (P-S6) are aberrantly upregulated in renal cysts in ADPKD and PKD mouse models, and mTOR inhibition with rapalogs reduced cyst growth and kidney enlargement and preserved renal function in PKD rodent models." (PMID 36002021, 2022). "Taken together, these findings indicate that, in the context of the jck mutation, a state of hyperproliferation of the cyst-lining epithelial cells ensued, in part, via increased p-ERK1/2, p-AKT, and mTOR activity, recapitulating rather precisely the ADPKD phenotype." (PMID 36326820, 2022). "mTOR is a critical regulator of cell proliferation and cyst expansion in ADPKD." (PMID 35748097, 2022). "Our data show that CaMK4 is a novel upstream regulator of mTOR and that CaMK4 inhibition may be a therapeutic approach to slowing cyst growth in ADPKD patients." (PMID 36002021, 2022). "Embryonic tissue from MCDK patients showed different expression patterns in a recent study, indicating that inappropriate mTOR pathway activation may be involved in cyst formation in MCDK." (PMID 36551779, 2022). "The effects of KN-93 were independent of the liver kinase B1–adenosine monophosphate-activated protein kinase (AMPK) pathway, and the combination of KN-93 and metformin, an AMPK activator, had additive inhibitory effects on mTOR signaling and in vitro cyst growth." (PMID 36002021, 2022). "Mammalian target of rapamycin (mTOR) is overactive in cyst-lining cells and contributes to abnormal cell proliferation and cyst enlargement; however, the mechanism for mTOR stimulation remains unclear." (PMID 36002021, 2022). "We then evaluated whether the enhanced proliferation was dependent on mTOR, since enhanced mTOR activity is suggested to support cyst formation." (PMID 34948309, 2021). "As AMPK activation leads to mTOR inhibition, which has been described earlier in this manuscript as a potential strategy to decrease cyst growth in mouse model, the activation of AMPK pathway may be a good target for therapeutic strategies." (PMID 32847032, 2020). "In a zebrafish model of polycystic kidney disease (PKD), combination treatment with the mTOR-dependent autophagy activator rapamycin, as well as the mTOR-independent autophagy activators carbamazepine and minoxidil, markedly attenuated cyst formation and restored kidney function." (PMID 31936109, 2020). "Our results suggest that, in addition to improving cyst metabolism, anti-miR-17 therapy could potentially alleviate cyst growth via regulation of the mTOR pathway." (PMID 30760828, 2019). "Thus, pathways that regulate glycolysis, either inhibiting (e.g., AMP-activated protein kinase, AMPKα) or activating (e.g., mTOR) it, also modulate cyst growth." (PMID 31336917, 2019).
cyst (continued). "Additionally, the activity of the energy sensor, adenosine monophosphate activated protein kinase (AMPK), is decreased, while the mammalian target of rapamycin (mTOR) signaling pathway is over-activated in cyst epithelial cells." (PMID 30886744, 2019). "So we concluded that DEHP exposure increased ROS and oxidative stress responsive miRNAs, then influenced the key genes in the PI3K/AKT1/mTOR signaling pathway and induced cell apoptosis in the newborn mouse ovaries, thereby influencing cyst breakdown and primordial follicle assembly." (PMID 31920986, 2019). "Only the high-dose group, at the early stage, showed histologically proven inhibition of cystogenesis and regression of cysts, pointing out that effective mTOR inhibition leads to a delay in cyst development and renal volume stabilization, but require higher doses and longer exposure to the drug." (PMID 30510618, 2018). "To determine why loss of Fnip1 could result in increased renal weight and cyst formation, we measured activation of AMPK and the mTOR pathways by immunoblotting and immunohistochemistry (IHC)." (PMID 29897930, 2018). "As neoplastic hyperplasia hardly occurs in cyst-lining cells, the mTOR pathway may be less distinctively detected in pulmonary cysts." (PMID 29357828, 2018). "We noted that the very few PI3K inhibitors that were effective at inhibiting cyst growth may also have activity against mTOR (e.g., NVP-BGT22625)." (PMID 28644734, 2017). "We previously used immunohistochemistry to demonstrate that the pneumocytes lining the cyst wall frequently express phospho-mTOR (p-mTOR) and phospho-S6 (p-S6), supporting the hypothesis that a subset of the lining cells active mTOR signaling." (PMID 26974543, 2016). "Moreover, application of mTOR inhibitor rapamycin reduced the size of the cyst-like structures formed by hICD-expressing cells." (PMID 24851866, 2014). "Studies in rodent models show that mTOR inhibition retarded hepatic cyst expansion." (PMID 23304619, 2012). "However, in this case, mTOR and other cAMP-independent pathways may have contributed to cyst enlargement, limiting its effect." (PMID 40051696, 2025). "In addition, downregulation of mTor in adult male GSCs and early germ cells causes non-autonomous activation of mTORC1 in neighboring cyst cells, which correlates with a disruption in the coordination of germline and somatic differentiation." (PMID 38512882, 2024). "In addition, mTOR signaling significantly contributes to cyst enlargement in ADPKD." (PMID 35892566, 2022). "The observed effect was mediated by the activation of the mTOR and MAPK/ERK signaling pathways, which, in turn, promoted the proliferation of cyst-lining cells." (PMID 40722668, 2025). "However, the rapid cyst growth suggests NF1 may have contributed to mTOR activation by ADPKD." (PMID 40051696, 2025). "Tolvaptan reduces cAMP levels, thereby limiting cyst fluid secretion, while metformin activates AMPK, inhibiting proliferative and secretory pathways such as mTOR and CFTR." (PMID 41254555, 2025). "Recent studies suggest that dysregulated chromatin remodeling enhances the activity of pro-cystogenic pathways, such as mTOR and STAT3, by increasing the accessibility of their promoter regions, thus promoting cell proliferation and cyst expansion." (PMID 40801635, 2025). "Beyond defective ciliary polycystin signaling, PKD pathogenesis involves dysregulation of multiple signaling pathways including mTOR, EGFR, and MAPK, which promote cyst expansion." (PMID 40507782, 2025). "mTOR pathway modulation represents another therapeutic avenue, as mTOR signaling is dysregulated in multiple NPH subtypes and its inhibition can reduce cellular proliferation and cyst growth." (PMID 40806500, 2025). "It works by activating AMPK, which inhibits both the CFTR (cystic fibrosis transmembrane conductance regulator) and mTOR pathways through the phosphorylation of TSC2 (tuberin), potentially impacting cyst growth and renal function." (PMID 39200287, 2024).
cyst (continued). "The aim of this study was to determine the effects of MET on cyst growth, kidney function, AMPK and mTOR signaling, and lactate levels in male PCK rats, a Pkhd1 gene mutation model of human autosomal recessive polycystic kidney disease (ARPKD)." (PMID 37653564, 2023). "The mechanism responsible for the positive effect of the restriction is thought to be the inhibition of the mTOR transduction pathway, which in ADPKD is pathologically hyperactive, leading to cyst growth and forced inhibition of AMPK." (PMID 37299584, 2023). "It has been demonstrated that the Ras/B-Raf/MEK/ERK and AKT/mTOR pathways are upregulated in ADPKD cells, which leads to increased cell proliferation and cyst enlargement." (PMID 35159293, 2022). "In conclusion, our study elucidated that GA retards MDCK cyst enlargement by inhibiting phosphorylation of the ERK1/2 and mTOR/S6K signaling pathways." (PMID 35744960, 2022). "Moderate food restriction slowed cyst growth through AMPK activation and mTOR signaling suppression in rodent models." (PMID 35328738, 2022). "These renal cysts responded to some drugs known to inhibit cyst formation in ADPKD, such as mammalian target of rapamycin (mTOR), indicating that these models can be used to screen drug compounds that prevent renal cyst formation." (PMID 33656639, 2021). "Activation of the mTOR pathway was observed in cyst lining epithelia of ADPKD kidneys and polycystin-1 was shown to negatively regulate mTOR activation." (PMID 32847032, 2020). "Histidine was preferentially used as a glucogenic amino acid favoring cyst growth while branched-chain amino acids (e.g., leucine) accelerated the ADPKD progression in mice likely through mTOR activation." (PMID 31336917, 2019). "mTOR signalling is upregulated in PKD and rapamycin slows cyst expansion, whereas renal inactivation of the Tsc genes causes cysts." (PMID 26931735, 2016). "The mammalian target of rapamycin (mTOR) inhibitor sirolimus (SIR) is an immunosuppressant with strong antiproliferative effects, and is potentially able to stop or reduce cyst growth and preserve renal function in ADPKD." (PMID 25899445, 2015). "Moreover, PC1 suppresses mTOR signaling by interacting with tuberin, and impaired GPCR signaling can disrupt this regulation, resulting in hyperactive mTOR and enhanced cyst development." (PMID 40801635, 2025). "These inhibitors have demonstrated promising results in preclinical models by more effectively suppressing mTOR signaling and reducing cyst proliferation without the feedback activation commonly associated with rapamycin analogs." (PMID 40801635, 2025). "Although mTOR inhibitors sirolimus and everolimus were shown to slow cyst growth in PKD rodents, they did not slow ADPKD in clinical trials." (PMID 38956234, 2024). "The use of mTOR inhibitors was more prevalent in AML/cyst-positive (45.3%) than -negative (23.5%) patients." (PMID 39027368, 2024). "This may be caused by continuous caloric excess, which strongly activates the mTOR pathway and suppresses AMPK, leading to cyst growth." (PMID 39203719, 2024). "Research involving kidney epithelial cell cultures and PKD mouse models has shown that metformin inhibits mTOR signaling and the cystic fibrosis transmembrane conductance regulator (CFTR), reducing epithelial proliferation and secretion, thereby slowing cyst growth." (PMID 39339816, 2024). "Parallels have been discussed to the cyst formation in LAM that might result from interactions between the estrogen signaling pathway and the mechanistic target of rapamycin (mTOR), in which both the tuberous sclerosis complex and FLCN are involved." (PMID 38020174, 2023). "Activated mTOR pathways stimulate the proliferation of LAM cells which express VEGF, allowing metastasis and angiogenesis into the lung tissue, leading to lung parenchymal destruction and cyst formation." (PMID 37435256, 2023).
cyst (continued). "Though mTOR is a key pathway for cyst growth, mTOR inhibitors are not recommended for treating ADPKD because of various side effects noted in clinical trials, including interfering with normal recovery from injury." (PMID 36203940, 2022). "Our findings in Six2Cre+Tfap2bfl/fl mice that survived to 1-2 months of age further show that lack of AP-2β activity results in β-catenin/mTOR hyperactivation and severe renal fibrosis and cyst formation that leads to renal failure already at an early age." (PMID 35468900, 2022). "Elevated mTOR activation is an established feature of PKD and is thought to contribute importantly to cell proliferation and cyst growth; however, the mechanism responsible for elevated mTOR activity remains unclear." (PMID 36002021, 2022). "Lack of KCTD1 resulted in β-catenin and mTOR hyperactivation, associated with increased expression of TGF-β1, and led to progressive renal fibrosis and cyst formation." (PMID 35468900, 2022). "The excessive proliferation of cyst epithelial cells is facilitated by dysregulation of numerous signaling pathways, including the Wnt, B-Raf/MEK/ERK, and mammalian target of rapamycin (mTOR) signaling pathways." (PMID 35457146, 2022). "Additionally, compelling evidence has shown that the overactivation of mTOR signaling encourages cyst growth and proliferation in PKD and that epithelial cells of cystic kidneys in ADPKD express elevated levels of mTOR activity." (PMID 36422197, 2022). "Since GA can inhibit mTOR/S6K expression, GA’s action for slowing MDCK cyst progression may involve the AMPK-dependent pathway." (PMID 35744960, 2022). "In an orthologous mouse model of human ADPKD (Pkd1flox/flox;Pkhd1-Cre), stevioside and steviol inhibited the CFTR expression and mTOR/S6K proteins by activating AMP-activated protein kinase, thereby delaying the cyst development through inhibiting proliferation of renal epithelial cells." (PMID 33986666, 2021). "We assayed these 5 compounds (the mTOR inhibitor Everolimus, the Chk1 inhibitor AZD-7762, the Ikk inhibitor IMD-0354 and the Plk1 inhibitors Volasertib and Rigosertib) in our Matrigel-based 3D assay and found that all inhibited cyst growth." (PMID 32144367, 2020). "Conversely, patients with ADPKD did not benefit from rapalogs treatment, indicating that mTOR-mediated signaling is not the only pathway involved in cyst formation." (PMID 28353628, 2017). "Preclinical trials based on mTOR inhibition (mTOR-I) by either the immunosuppressant sirolimus (SIR) or everolimus (EVER) demonstrated that the sirolimus injection led to increased kidney size, cyst density and tubular cell proliferation." (PMID 28353628, 2017). "Here we show that dysregulation of the GSK3β/β-catenin, but not mTOR/S6 pathway is another crucial player for Dicer-dependent cyst development." (PMID 25799508, 2015). "mTOR inhibition (mTOR-I) by either SIR or everolimus (EVER) has been investigated in preclinical studies and clinical trials but only subtle, if any, clinically relevant effects on cyst growth and the preservation of renal function were found." (PMID 25899445, 2015). "In the kidney, the expression of p-Akt (Ser473), p-mTOR (Ser2448) and p-S6 was increased in collecting tubule-derived cyst epithelium of the PCK rat without NVP-BEZ235 treatment compared to those in the renal tubules of normal rat." (PMID 24498161, 2014). "Our data suggest that FPC modulates the activities of the PI3K/Akt/mTOR pathway and that the expression of FPC C-tail may antagonize the function of the full-length protein and promote cyst formation." (PMID 24851866, 2014). "Furthermore, downregulation of mTor in adult GSCs and early germ cells leads to a striking non-autonomous activation of mTORC1 in neighboring cyst cells, which correlates with precocious differentiation." (PMID 38512882, 2024).